CDK2 (cyclin dependent kinase 2)
Diseases named in the same sentence as CDK2 in open-access papers (continued):
Sharing a sentence is not in itself a finding about the gene and the disease.
pancreatic cancer (33 papers, 2011 to 2026). "The molecular mechanism of the various fate of pancreatic cancer cells upon CDK4/6 inactivation is associated with the modulation of CDK2 activity." (PMID 30340359, 2018). "In addition, studies have found that pancreatic cancer tumor growth and proliferation are related to CDK2/4/6 activation caused by CDKN2A deletion, and CDKN2A is closely related to the malignancy of esophageal squamous cell carcinoma." (PMID 38206516, 2024). "Treatment of pancreatic cancer cells with pristimerin also resulted in G1-phase arrest which was strongly associated with a marked decrease in the level of cyclins (D1 and E) and cyclin-dependent kinases (cdk2, cdk4 and cdk6 ) with concomitant induction of WAF1/p21 and KIP1/p27." (PMID 22952775, 2012). "ZC3HAV1, a PARP family enzyme, has been shown in pancreatic cancer to regulate cell cycle progression by modulating cyclin D1 and CDK2, and to bind KRAS, enhancing its expression and activating ERK signalling to promote proliferation and metastasis." (PMID 41596441, 2026). "CDK2 inhibition exerts anti-neoplastic effects against diverse aneuploid cancers including lung, colon, and pancreatic cancers." (PMID 38031910, 2023). "In pancreatic cancer, MBOAT2 overexpression increases CDK2 and CCNA2 expression levels, causing the cell cycle to advance from the G1 to the G2 phase." (PMID 37240761, 2023). "Over-expression of KIF15 increases the cyclin-D1, CDK2, p-RB expression, and accelerated G1/S transition in pancreatic cancer cells." (PMID 35359374, 2022). "Overexpression of Roundabout homolog 1 caused S-phase arrest to inhibit pancreatic cancer cell proliferation by significantly reducing the expressions of CCNA2 and CDK2." (PMID 35246013, 2022). "Consistently, ERBB2 knockdown also decreased cyclin A, cyclin B, CDK1, and CDK2 protein contents in both pancreatic tumor cells." (PMID 35343383, 2022). "GW-8510, an inhibitor of CDK2, has a similar effect to gemcitabine in inhibiting pancreatic cancer cells." (PMID 35087757, 2021). "We observed that the treatment of pancreatic cancer cells with honokiol resulted in G1-phase arrest of cell cycle progression, along with reduction in cyclin D1, cyclin E, Cdk2 and Cdk4 and increase in p21 and p27 at the protein level." (PMID 21720559, 2011). "Similarly, CACYBP knockdown in pancreatic cancer inhibits cell growth by blocking the G1-to-S phase transition, mediated by the downregulation of Cyclin E, Cyclin A, and CDK2, along with the upregulation of p27ˆKip1 and Rb." (PMID 40167359, 2025). "We have further shown that miR-141 could inhibit the proliferation of pancreatic cancer cells by upregulating p27 and downregulating CDK2 and cyclin E through its regulatory effects on NRP-1." (PMID 31572065, 2019). "Eventually, in vitro toxicity could be reported in a variety of cancer cell lines including pancreatic cancer by the inhibition of CDK2 and CDK9." (PMID 30340359, 2018). "Our data revealed a dose-dependent decrease in the expression of cyclins (D1 and E) and cyclin-dependent kinases (Cdk2 and Cdk4); while an induced expression of cyclin-dependent kinase inhibitors (p21 and p27) was observed after honokiol treatment in both MiaPaCa and Panc1 pancreatic cancer cells." (PMID 21720559, 2011). "Importantly, in pancreatic cancer, the anti-tumorigenic activity of IL-33 has been demonstrated through tumor cell-intrinsic downregulation of cellular proliferating proteins, such as CDK2 and CDK4, and upregulation of pro-apoptotic molecules, such as Bax and TRAIL." (PMID 34209038, 2021). "In our patients with pancreatic cancer, SPOP insufficiency led to higher expression of CDK2 and the EMT-related protein Snail." (PMID 31624231, 2019). "In all four pancreatic cancer cell lines tested, we found decreased expression of cell cycleproteins, including E2F1, Cyclin D1, Cyclin E, Cdk2, Cdk4 and Cdk6, and increased expression of p21 and p27." (PMID 23028659, 2012).
pancreatic cancer (continued). "The observed inhibitory effects of pristimerin on cyclin D1, cyclin E, cdk2, cdk4 and cdk6, along with its upregulating effects on WAF1/p21 and KIP1/p27 in pancreatic cancer cells suggest its potential in disruption of the uncontrolled cell cycle progression." (PMID 22952775, 2012). "Due to the amplification of acquired CCNE1 in breast and pancreatic cancers, the cells have acquired resistance to CDK4/6 inhibitors in vitro, damaging the sensitivity of cells to CDK4/6 inhibitors but still rendering them sensitive to CDK2 inhibitors." (PMID 39648148, 2024). "Over-expression of Cyclin D1 was found to confer gemcitabine and cisplatin resistance to pancreatic cancer cell; CCNE1, CDK2, and CDKN1A, previously reported to be up-regulated by gemcitabine as confirmed in our study, were also implied in chemotherapy resistance." (PMID 33925948, 2021). "Collectively, our results demonstrated that TNFR2 promotes tumorigenesis and progression of pancreatic cancer via dual effect: suppressing cancer immunogenicity via the TNFR2-NFκB p65-PDL1 pathway and partially accelerating tumor growth via the TNFR2-NFκB-survial pathways (c-Myc, cyclin D and CDK2)." (PMID 35260434, 2022).
triple-negative breast carcinoma (24 papers, 2016 to 2025). An invasive breast carcinoma which is negative for expression of estrogen receptor (ER), progesterone receptor (PR), and human epidermal growth factor receptor 2 (HER2). "Co-inhibition of EGFR and ROCK in triple-negative breast cancer cells caused decrease in phosphorylated pRB, p27, Cyclin A and Cdk2 protein levels, correlating with an almost complete loss of the ability of the cells to replicate and consequently, proliferate." (PMID 27374095, 2016). "Inhibition of CDK2 resulted in increased Smad3 activity and decreased triple-negative breast cancer (TNBC) cell migration." (PMID 35592410, 2022). "Single-cell assessment of CDK2 activity has confirmed difference in cell-cycle regulation between the luminal androgen receptor (LAR) subtype of triple negative breast cancer (TNBC) and basal-like cells." (PMID 36266723, 2022). "Similarly, TRIM32 is an E3 ligase and CDK2 substrate that mediates the CDK2 promotion of radio resistance in triple-negative breast cancer." (PMID 38727267, 2024). "The cyclin E/CDK2 complex may present a promising target axis for the treatment of triple-negative breast cancers (TNBC); however, therapeutically relevant doses of CDK2 inhibitors have been associated with toxicities." (PMID 35884422, 2022). "EZH2 phosphorylation by CDK2 promotes progression of triple-negative breast cancer (TNBC)." (PMID 31704972, 2019). "For example, miR-638 regulates cell differentiation and proliferation by targeting cyclin-dependent kinase 2 (CDK-2) in leukemic cells; and in BRCA1-deficient triple negative breast cancer tumors, miR-638 and miR-146 were suggested to perform as potential biomarkers for improved overall survival." (PMID 29263143, 2018). "Thus, CDK2 inhibitors may restore chemosensitivity in chemoresistant triple negative breast cancer cases." (PMID 32380689, 2020). "In triple-negative breast cancer models, KLT effectively blocked cell cycle progression at the G2/M phase by downregulating CDK1, CDK2, and CHEK1, inhibiting CDC25A, CDC25B, MELK, and AURKA activity, suppressing mitosis, and inducing apoptosis." (PMID 41164166, 2025). "Another functional study has shown that CDK2-mediated phosphorylation of EZH2 induces and preserves proliferation of triple-negative breast cancer cells." (PMID 36266723, 2022). "A novel CDK2/9 inhibitor, CYC065, was applied with eribulin to suppress the growth of triple negative breast cancer cells." (PMID 35053380, 2022). "A recent study has revealed that Cdc25 inhibitors effectively target the triple negative breast cancer refractory to CDK4/6 and CDK2 inhibition." (PMID 30135856, 2018). "This study reported our most recent results for targeting triple-negative breast cancer (TNBC) with a low survival rate, using CR6-interacting factor 1–cyclin-dependent kinase 2 (CRIF1–CDK2) interface inhibitors, by inhibiting the resistance to taxol treatment." (PMID 35205737, 2022). "In addition to its ability to inhibit CDK1 and CDK2, dinaciclib abrogates CDK12 activity and suppresses the expression of BRCA1, BRCA2, and Rad5, thereby sensitizing BRCA-wild type triple negative breast cancer to PARP inhibition." (PMID 30135856, 2018). "CYC065, a CDK2/9 inhibitor, could induce decreased cell migration/invasion and impede the epithelial-mesenchymal transition (EMT) program in triple-negative breast cancer mainly through inhibition of CDK2-mediated phosphorylation of Smad333." (PMID 29789536, 2018). "Activation of CDK2 in triple negative breast cancer (TNBC) can contribute to non-canonical phosphorylation of a TGFβ signaling component, Smad3, promoting cell proliferation and migration." (PMID 29137393, 2017). "Additionally, CDK2 inhibition has been found to be synergistic with the non-taxane anti-mitotic agent erilbulin in triple negative breast cancer in vitro and in xenograft models." (PMID 32380689, 2020).
triple-negative breast carcinoma (continued). "Inhibition of CDK4/6 and CDK2 function using biochemical inhibitors suppresses the growth of triple negative breast cancer cells with low PPM1A, suggesting PPM1A as a biomarker to predict sensitivity to CDK inhibitors for more effective treatment of triple negative breast cancer." (PMID 31372497, 2019). "For example, the lack of sensitivity of some triple-negative breast cancer cells may reflect both a decreased dependence on CDK4/6 activity for cell cycle entry (due to high cyclin E expression and CDK2 activity) and low p21 and/or p27 levels." (PMID 34784791, 2021).
acute myeloid leukemia (22 papers, 2015 to 2025). Acute myeloid leukemia (AML) is a group of neoplasms arising from precursor cells committed to the myeloid cell-line differentiation. "TRIM21 mediates the degradation of the autophagic lysosomal pathway of cyclin-dependent kinase 2 (CDK2) to inhibit the proliferation of acute myeloid leukemia." (PMID 39154024, 2024). "AT-7519 is the second generation multi-CDK inhibitor that targets CDK1/2/4/6/9 and has proven effective in inhibiting hematologic malignancies, while BMS-387032 is a selective CDK2 inhibitor that has shown promise in treating acute myeloid leukemia in vitro." (PMID 35205315, 2022). "The association of ubiquitin‐dependent degradation of CDK2 with the arrest of tumour growth in acute myeloid leukemia (AML) cells supports this hypothesis." (PMID 33124043, 2021). "PRDX2, the peroxidase activity of which is activated by CDK2, inhibits the differentiation of acute myeloid leukemia (AML) cells." (PMID 33771165, 2021). "No pertinent data concerning solid tumours is available but sunitinib has been demonstrated to diminish cdk2 in acute myeloid leukaemia cells." (PMID 25444514, 2015). "The inactivation of cyclin‐dependent kinase 2 (CDK2) effectively overcomes the blocking of cell differentiation in acute myeloid leukemia (AML) and is therefore a promising and potential approach for the treatment of AML." (PMID 37261210, 2023). "Inactivation of CDK2 has been shown to effectively overcome the differentiation arrest of acute myeloid leukemia (AML) cells." (PMID 36266723, 2022). "In a later study, it was verified that Kelch-like protein 6 (KLHL6), as an E3 ubiquitin ligase, plays an important role in acute myeloid leukemia (AML) by regulating the expression of CDK2." (PMID 34072267, 2021). "ST has been reported to be capable of directly binding to CDK2 with subsequent CDK down-regulation and G1 arrest in acute myeloid leukaemia cells." (PMID 36230567, 2022). "Recent studies also suggest that inhibiting CDK2 could be a promising therapeutic strategy to treat acute myeloid leukemia (AML)." (PMID 34771669, 2021). "However, there are some ongoing clinical trials combining fadraciclib (multi‐CDK2, 9 inhibitor) and ABT‐199 against relapsed/refractory CLL (NCT03739554), relapsed/refractory acute myeloid leukemia and myelodysplastic syndrome patients (NCT04017546) which will shed light on this field." (PMID 37704591, 2023). "Other studies reported that cyclin-dependent kinase 2 triggers the degradation of C/EBPα through SKP2 in acute myeloid leukemia (AML), and that SKP2 ubiquitinates C/EBPα through physically interacting with the C-terminal portion of C/EBPα in AML." (PMID 41081508, 2025).
non-small cell lung carcinoma (21 papers, 2013 to 2025). A group of at least three distinct histological types of lung cancer, including non-small cell squamous cell carcinoma, adenocarcinoma, and large cell carcinoma. "PIWIL2 drives the progression of non-small cell lung cancer through the induction of CDK2 and Cyclin A expression, thereby inhibiting apoptosis, and G2/M cycle arrest." (PMID 39717847, 2024). "CCND1 and CDK2 were both expressed in non-small cell lung cancer, and CCND1 was highly expressed in non-small cell lung cancer tissues (42%)." (PMID 38245694, 2024). "Downregulation of YTHDF1 expression inhibits non-small-cell lung carcinoma (NSCLC) cell proliferation by regulating the translation of CDK2, CDK4, and CCND123." (PMID 35637959, 2022). "YTHDF1 promotes the proliferation of non-small cell lung cancer (NSCLC) cells by enhancing the translational efficiency of cell cycle regulators CDK2, CDK4 and cyclinD1." (PMID 33928028, 2021). "Roscovitine is a CDK2/7/9 inhibitor in clinical trials for the treatment of non-small cell lung cancer (NSCLC), Cushing’s disease, leukemia, multiple myeloma, HIV infection, herpes simplex infection, cystic fibrosis, and chronic inflammation disorders." (PMID 32903585, 2020). "This study suggested the possible clinical use of cyclin-dependent kinase 1 as a predictor of recurrence and cyclin-dependent kinase 2 as a predictor of overall survival in early-stage non-small cell lung cancer." (PMID 25301183, 2014). "CFI-400945 treatment causes polyploidy, tumor growth inhibition and apoptosis; synergizes with CDK2 (cyclin-dependent kinase 2) inhibitor seliciclib; leads to radiosensitization in non-small cell lung cancer cell lines and enhances radiation-induced tumor growth delay in xenograft models." (PMID 41092110, 2025). "In addition, YTHDF1 promoted non-small cell lung cancer cell proliferation through regulating the translational efficiency of CDK2, CDK4, and cyclin D1." (PMID 33726814, 2021). "After evaluating YTHDF1’s role in advancing tumor cell cycle progression, we examined its known targets, CDK2 and CDK4, in non-small cell lung cancer using RNA Binding Protein Immunoprecipitation Assay (RIP)." (PMID 40251202, 2025). "DF1, as an oncogene, has been reported to increase G0/G1 cells by regulating CDK2, CDK4, and cyclin D1 translational efficiency in non-small cell lung cancer (NSCLC)." (PMID 35351856, 2022). "When non-small cell lung cancer (NSCLC) cells were in a normoxia state, overexpression of YTHDF1 promoted tumor cells proliferation and xenograft tumor formation by augmenting the translations of m6A-marked CDK2, CDK4, and cyclinD1, three key regulators in the G0/G1 cell cycle transition." (PMID 32276589, 2020).
osteosarcoma (21 papers, 2008 to 2024). A usually aggressive malignant bone-forming mesenchymal neoplasm, predominantly affecting adolescents and young adults. "This study demonstrated that BMS-794833 mitigated anlotinib resistance in osteosarcoma by acting on the VEGFR/Ras/CDK2 pathway." (PMID 38532893, 2024). "Here, we found that BMS-794833 reduced anlotinib resistance in osteosarcoma by targeting the VEGFR/Ras/CDK2 pathway." (PMID 38532893, 2024). "This study demonstrated that BMS-794833 regulated the proliferation of osteosarcoma cells through CDK2." (PMID 38532893, 2024). "Based on the expression pattern of CDK2 in osteosarcoma samples in the GEO dataset and the relationship of CDK2 with survival in patients with osteosarcoma in TCGA dataset, CDK2 was found to play an important role in the development of osteosarcoma." (PMID 38532893, 2024). "In conclusion, this study demonstrated that BMS-794833 attenuated anlotinib resistance in osteosarcoma by targeting the VEGFR/Ras/CDK2 pathway." (PMID 38532893, 2024). "Owing to its important role in tumor progression, CDK2 is a potential therapeutic target for osteosarcoma." (PMID 38532893, 2024). "The effects of BMS-794833 on the proliferation and drug resistance of osteosarcoma cells were found to be dependent on the VEGFR/Ras/CDK2 signaling pathway." (PMID 38532893, 2024). "In this study, we found that BMS-794833, a novel small-molecule drug, improved the sensitivity of osteosarcoma to anlotinib by targeting the VEGFR/Ras/CDK2 pathway." (PMID 38532893, 2024). "The results of rescue experiments showed that the regulatory effects of BMS-794833 on the proliferation and drug resistance of osteosarcoma cells were dependent on the VEGFR/Ras/CDK2 pathway." (PMID 38532893, 2024). "Mechanistically, BMS-794833 enhanced the sensitivity of osteosarcoma to anlotinib by targeting the VEGFR/Ras/CDK2 pathway." (PMID 38532893, 2024). "Altogether, these results indicate that BMS-794833 inhibits the proliferation of osteosarcoma cells through the VEGFR/Ras/CDK2 axis and enhances the sensitivity of osteosarcoma cells to anlotinib." (PMID 38532893, 2024). "CDK2 is considered to play an important role in osteosarcoma, as its overexpression or enhanced activity has been associated with aggressive tumor behavior, metastasis, and poor patient prognosis." (PMID 38532893, 2024). "MiR‐145‐5P inhibits osteosarcoma cell proliferation by targeting inhibit of E2F3b, which affected Cyclin D1, CDK2, CDK4 and CDK6 expression." (PMID 34741389, 2021). "In our study, the levels of the CDK2 were significantly decreased in the osteosarcoma U2OS-siRTKN2 cells, which was in complete agreement with the results showing the induction of cell cycle arrest in G1 phase in the U2OS-siRTKN2 U2OS cells." (PMID 30389712, 2018). "We evaluated the clinical impact of CDK2 overexpression on a series of 21 high-grade osteosarcoma (OS) samples profiled by using cDNA microarrays." (PMID 27898692, 2016). "It is suggested that the CRIF1–CDK2 interface inhibitor could improve cellular radio sensitivity in the osteosarcoma (OS) cell lines by selectively enhancing arrest in the G2/M phase and apoptosis associated with CDK2 overactivation in these cells." (PMID 35205737, 2022). "In addition to CCND3 amplifications, amplifications of CCNE1 are common in osteosarcoma as well and the effect of CDK2 inhibition on tumor growth has been demonstrated by dinaciclib (SCH 727965) using patient‐derived xenografts." (PMID 33963544, 2021). "In this study, it was found that PNS could facilitate p27 expression while suppressing the expression of cyclin D1 and CDK2, so as to arrest osteosarcoma cells in the G0/G1 phase." (PMID 34659528, 2021). "Inactivation of CDK1 and CDK2 triggered the apoptosis of osteosarcoma cells." (PMID 26337976, 2015). "However, whether BMS-794833 regulated osteosarcoma through the VEGFR/Ras/CDK2 axis was unclear." (PMID 38532893, 2024).